INS (insulin)
Diseases named in the same sentence as INS in open-access papers (continued):
Sharing a sentence is not in itself a finding about the gene and the disease.
Obesity (continued). "The secretion of fatty acids from adipocytes in obesity induces the unfolded protein response (UPR) pathway and by activating the JNK and inhibiting the expression of chaperone proteins and ER-associated degradation (ERAD), insulin resistance occurs in the liver." (PMID 37876013, 2023). "It is of note that the obesity phenotype of mc3r knockout mice are different from mc4r knockout mice, mc3r knockout mice do not exhibit significantly increased food intake, increased weight, and substantial insulin resistance, while they have increased fat mass and feed efficiency." (PMID 38322156, 2023). "The gut microbes can influence body weight, insulin sensitivity, or glucose and lipid metabolism; thus, some authors have reported that changes in the microbiota may be important in the pathogenesis of obesity and metabolic syndrome." (PMID 37764746, 2023). "In line with this hypothesis, the overconsumption of food and, ultimately, obesity relate to metabolic impairments reflected by reduced insulin sensitivity, possibly insufficient GLP-1 signalling, notable alterations in mesoaccumbens DA function and impaired outcome learning." (PMID 37592007, 2023). "A possible explanation could be that TyG-BMI, TyG-WC and TyG-BMI were adjusted indexes with indicators of insulin sensitivity and obesity including glucose, insulin level, BMI, WC and WHtR, which were also suggested with good predictive performance for T2DM in previous study." (PMID 36742412, 2023). "Thus, potential mechanisms underlying the association of obesity with CRC pathogenesis include adipocytokine imbalance, insulin resistance, changes in the insulin-like growth factor (IGF)-1/IGF-1 receptor (IGF-1R) axis, and chronic inflammation and oxidative stress." (PMID 37048534, 2023). "Obesity and hepatic steatosis are known to strongly induce SCD1 expression, whereas rodents that are specifically deficient in SCD1 in the liver are protected from developing hepatic steatosis by reducing lipid synthesis and increasing FFA β-oxidation and insulin sensitivity." (PMID 37361533, 2023). "However, this pathway may only show a compensatory response when the insulin signaling pathways are turned off, supporting the important role of insulin regulation in obesity." (PMID 37505559, 2023). "In addition to finding correlations between obesity and the salivary measures of insulin, CRP, and adiponectin, the progressive nature of their suggested scoring system, as opposed to the binary definition of the disease in adults, revealed a higher level of sensitivity for pediatric populations." (PMID 36831972, 2023). "Furthermore, anti-obesity and insulin sensitizing effects have also been endorsed by the modulating potential of C. odorata and coumarin on adipokinin levels (leptin, adiponectin, and chemerin), and inflammatory (TNFα, IL-6) and oxidative stress biomarkers (CAT, SOD, MDA)." (PMID 37033655, 2023). "Similarly, studies using the pharmacological mitochondria-targeted antioxidants MitoQ or MitoTEMPO have shown improvements in fasting blood glucose, insulin, lipid levels, and glucose and insulin tolerance in rodent models of high-fat diet (7–8 weeks)-induced obesity." (PMID 37238003, 2023). "However, in individuals with obesity, their bodies may become less responsive to the effects of insulin, leading to elevated glucose levels in the bloodstream and an augmented likelihood of developing T2D." (PMID 37600709, 2023). "Interestingly, chronic muscle stimulation, which improves the mitochondrial respiratory function and corrects mitochondrial morphological changes, ameliorates mitochondrial function in obesity by reducing muscle ceramide content and improving insulin-stimulated glucose uptake." (PMID 37762318, 2023).
Obesity (continued). "During obesity-related metabolic decline, genetic and epigenetic modifications leading to increased collagen and inflammatory cytokine production, cell senescence, and death restrain the capacity of adipocytes to effectively respond to various external signals, particularly insulin." (PMID 38137473, 2023). "Another obesity-related immunologic cell alteration takes place locally in adipose tissue and comprises lower B-regulatory and invariant NK cell numbers within the adipose tissue that results in inflammatory cell infiltration, decreased insulin sensitivity, and dysregulation of adipokine secretion." (PMID 37065759, 2023). "Consequently, treatments based on miRNA that target these adipocyte depots may be able to overcome obesity, insulin resistance, and malfunction of the adipose tissue." (PMID 37930593, 2023). "Moreover, also Akkermansia muciniphila has been recently characterized as a beneficial player in body metabolism because of its capability to reduce obesity by regulating metabolism and energy hemostasis and improving insulin sensitivity and glucose hemostasis." (PMID 37125045, 2023). "Thus, unlike in obesity, increased hepatic C16:0 during CR appears to be associated with improvements in insulin sensitivity." (PMID 37096321, 2023). "A previous study discovered that plasma fasting insulin and leptin levels decreased in the GLP-1 (rhGLP-1) Beinaglutide (BN) treated mice, suggesting that BN could reduce hyperinsulinemia and hyperleptinemia associated with obesity." (PMID 37025414, 2023). "Infusions of beta-endorphins increased plasma levels of the pancreatic hormones insulin, C peptide, and glucagon and also elevated plasma glucose levels in young patients with obese relatives, which suggests the involvement of opioid peptides in metabolic events related to obesity." (PMID 36830844, 2023). "If some of these bacterial metabolites may exert beneficial health effects, such as SCFAs and indole derivatives, others like LPS and TMAO may play detrimental roles leading to inflammation, oxidative stress and insulin resistance in the context of obesity and vascular complications." (PMID 38136564, 2023). "Although causality has not been determined, physical activity could positively impact periodontitis directly, by reducing inflammatory biomarkers, and indirectly, through its modulatory effects on insulin sensitivity, obesity, bone density, stress, and other health promoting behaviors." (PMID 38024148, 2023). "Moreover, factors associated with uncontrolled BP (≥140/90) were male gender (OR=1.4), age 50–59 years or at least 60 years (OR=3.3 and 6.6, respectively), overweight and obesity (OR=1.6 and 1.4, respectively), insulin use (OR=1.6), and LDL at least 100 mg/dl (OR=1.4)." (PMID 37008178, 2023). "Because several previous studies showed no or weak associations with CVD risk factors (e.g., inflammation, obesity, and insulin sensitivity), we might not expect any major association of AMY1 copy number and CVD risk." (PMID 36691017, 2023). "For instance, obesity instigates a shift in the composition of muscle fibers, favoring a transition towards a glycolytic phenotype, thereby leading to ectopic lipid accumulation and insulin resistance in SKM, ultimately hastening the progression of metabolic abnormalities." (PMID 37627494, 2023). "This is further supported by a recent study that has stratified children exposed to metformin alone and those exposed to insulin alone and shown that there was no increased risk in obesity associated with metformin exposure, relative to insulin, in children aged between 1 week and 11 years of age." (PMID 37597238, 2023). "The heart is a critical insulin-responsive organ that might develop IR due to obesity." (PMID 37608837, 2023).
Obesity (continued). "Studies based on glycine supplementation reported that adding glycine to the diet increased the insulin response and glucose tolerance, and with a proper dose it was remarkably successful in decreasing other metabolic disorders, many inflammatory diseases, a few types of cancers and obesity." (PMID 37569834, 2023). "The main objective of this study was to assess potential factors, particularly insulin, that may be responsible for the weight gains in sub‐phase 2a and their role in the subsequent increase in fat mass and obesity in sub‐phase 2b and insatiable appetite in phase 3." (PMID 37546289, 2023). "Moreover, leptin prevents obesity by promoting satiety and reducing hunger and insulin sensitivity." (PMID 37363537, 2023). "In the presence of obesity, therefore, it seems that myocytes also release proinflammatory cytokines (myosins), such as IL-6 and TNFα, in a synergic effect of the activity of myocytes and adipocytes on metabolic dysregulation, aggravating insulin resistance and inflammation." (PMID 36626317, 2023). "Importantly, endogenous insulin secretion may be maintained at type 1 diabetes diagnosis (particularly in individuals with obesity), but rapidly fall." (PMID 37728732, 2023). "Several mechanisms for the PWS obesity etiology were proposed, including disruption in limbic–hypothalamic pathways of satiety control, resulting in hyperphagia, alterations in hormones regulating food intake, a reduced energy expenditure, and insulin resistance." (PMID 37571382, 2023). "However, it remains unclear which mechanism is responsible for different regulation of D5D by insulin in obesity, compared with D9D and D6D." (PMID 37545582, 2023). "Among the two forms of SphK (SphK1 and SphK2), SphK1 expression is increased in insulin sensitive tissues but also in islets of Langerhans from mice under high fat diet (HFD) and in T2D patients, suggesting that this enzyme is involved in the onset of T2D associated with obesity." (PMID 37628901, 2023). "As an endogenous molecule (akin to insulin), therapeutic administration of PEPITEM may provide the opportunity to re-establish control over both local and systemic metabolic and inflammatory processes underlying the pathogenesis of obesity." (PMID 36891817, 2023). "Furthermore, 3-OH phloretin enhances insulin sensitivity during the progression of obesity." (PMID 36838843, 2023). "Indeed, activation of insulin signaling cascade in muscle and liver cells is inhibited by the accumulation and trafficking of lipid messengers such as ceramides and diacylglycerols that are elevated in obesity." (PMID 37441501, 2023). "In addition to vascular changes, high fructose consumption has been shown to reduce plasma insulin and leptin levels and increase ghrelin concentrations, which may contribute to obesity and thus a pro-inflammatory state." (PMID 38201956, 2023). "However, although bile acids have an insulin-sensitizing effect and facilitate intestinal fat absorption, being involved in carbohydrate and lipid metabolism, which contribute to obesity and T2DM pathogenesis, their precise role remains unclear." (PMID 37175468, 2023). "However, some of its peptides are unclear, for instance, resistin, an antagonist polypeptide of insulin action that may play a role in obesity." (PMID 36466401, 2022). "Leptin, a 16 kDa protein secreted by adipocyte and the key cytokine linked with obesity and T2DM, acts as an anorectic hormone that restricts lipid storage and body weight gain, inhibits ectopic lipid accumulation, attenuates lipotoxicity, and improves insulin sensitivity." (PMID 36046814, 2022). "Moreover, IL-8 seems to participate in promoting obesity, inflammation and IR, by attracting additional adipocytes and immune cells in the adipose tissue, and by interfering with insulin signaling by downregulation of adiponectin and/or activation of the p38 MAPK pathway." (PMID 36498901, 2022).
Obesity (continued). "Although exploratory in nature, this study raises the hypothesis that several metabolites, related to defective β-cell secretory function including adiponectin, glutamine, insulin secretory index HOMA-β%, pyruvate and gGT may contribute to improved GDM risk assessment in women with obesity." (PMID 36295825, 2022). "In addition, the dietary administration of CP, AG, and their combination significantly triggered the first phase of insulin secretion after oral glucose load, suggesting that these prebiotics synergically contribute to protect ß-cell function in diet-induced obesity." (PMID 36052065, 2022). "(Section 2), insulin enhances apelin expression in human and mouse adipocytes, suggesting the existence of a regulating loop that may promote apelin secretion during obesity as a compensatory mechanism to adapt to enhanced insulin requests." (PMID 35628332, 2022). "Obesity influences metabolic pathways including lipogenesis, lipolysis, and insulin signaling and leads to widespread accumulation of a range of lipid species, known as lipotoxicity; however, the mechanisms of lipotoxicity and how it is linked to pathophysiology remain unknown." (PMID 35906462, 2022). "Interestingly, we found that total serum dihydroceramides and individual species were significantly greater in individuals with obesity and T2D compared with athletes and lean individuals, with C18:0 species showing the strongest inverse relationship to insulin sensitivity." (PMID 36030929, 2022). "In addition to direct effects, OGT-driven changes in adipose insulin sensitivity and macrophage cytokine secretion may further fuel lipolytic dysfunction in obesity." (PMID 36111295, 2022). "Furthermore, a strategy of serial fetal AC measurements to guide insulin treatment initiation is subject to inherent measurement errors, which may be even more substantial with increasing pre-pregnancy overweight and obesity." (PMID 35627517, 2022). "During obesity, the nutrient surfeit leads to the development of hyperglycaemia and hyperlipidaemia, which increases the metabolic load and promotes the ectopic storage of lipids in different tissues—including the pancreas —triggering insulin resistance and chronic inflammation." (PMID 35628332, 2022). "In a context of obesity, the accumulation of proinflammatory macrophages in adipose tissue has an important role in the development of systemic inflammation, which is now recognized as a major actor in the development of insulin resistance in insulin-sensitive tissues, including SkM." (PMID 35806052, 2022). "Interplay between hormones and cytokines may also be important as TNFα, which reduces insulin sensitivity and has been shown to be overexpressed in people with obesity, is partially mediated by leptin in addition to IL-2, and IL-6 cytokines that increase T-cell expansion and liver disorders." (PMID 36143948, 2022). "Over activation of beta-adrenergic signaling, as seen in obesity, may additionally potentiate insulin resistance by directly interfering with glucose uptake and insulin signaling as recently shown in response to acute stress, and this mechanism might also occur in obesity." (PMID 36074318, 2022). "In the present study, we demonstrate that colesevelam reduces Western diet-induced obesity and associated metabolic dysregulation in mice, as indicated by a significantly lower body weight gain and better insulin response compared with control mice that do not receive the bile acid binder." (PMID 35075592, 2022). "However, while it has been shown that certain proinflammatory cytokines such as TNFα and IL-1β induce hepatic IGF-1 resistance, the contribution of IL-6 signaling in obesity-induced inflammation to hepatic insulin and IGF-1 downstream signaling remains controversial." (PMID 35628414, 2022).
Obesity (continued). "Indeed, PPARG may contribute to obesity by controlling food intake and appetite, not only through changes in insulin sensitivity, but also by regulating the transcription of the leptin gene, which is a key regulator of the central control of eating behavior." (PMID 36558537, 2022). "Similar to aged mice, inhibition of MT1-MMP activity led to normalization of hyperinsulinemia, improved glucose tolerance, enhanced insulin sensitivity and significant reduction of sIR levels in diabetic mouse models including db/db mice and mice with high-fat diet-induced obesity." (PMID 35768470, 2022). "During aging, regulation and renewal of adipose tissue cells may be disrupted due to the altered insulin signaling and differentiation potential of senescent MSCs, promoting the development of serious metabolic diseases, including metabolic syndrome and obesity." (PMID 36467400, 2022). "Accordingly, the compromised brain effect of endogenous or peripherally administered insulin in obesity might stem primarily from attenuated insulin transport to the brain as a result of hyperinsulinaemia, which can be overcome by directly targeting the brain with IN insulin." (PMID 35397638, 2022). "Because vitamin D is important in body fat, insulin sensitivity, adipogenesis and lipid accumulation, as well as cytokine and inflammatory signaling in adipose tissue, the health consequence of low serum 25(OH)D on adipose metabolic functions in obesity is highly documented." (PMID 36120442, 2022). "Therefore, hyperglycemic microenvironments rich in insulin, TCR ligands, and leptin, such as the ones associated with obesity and T2D, tend to result in inflammatory and metabolic diseases that impact the individual risk of developing other chronic co-morbidities." (PMID 36033972, 2022). "In addition, aging, obesity, and insulin dosage are positive determinants of circulating FGF21." (PMID 35192641, 2022). "In vitro and in vivo studies that model obesity related disorders have demonstrated that oligonucleotide technologies can be implemented to improve the metabolism of cells and tissues, exemplified by improvements in fat utilization and hepatic insulin signaling, respectively." (PMID 35295579, 2022). "Moreover, the TRF may lead to improved glycemic responses, insulin sensitivity, and glycemic variability throughout the day in volunteers with overweight or obesity." (PMID 36432465, 2022). "Further work is necessary to unravel the host-microbial mechanisms driving the BCAA metabolism to BCHA and whether targeting the enzymatic machinery involved in the production of these hydroxyl BCAA congeners could improve insulin sensitivity and liver diseases in obesity." (PMID 35292630, 2022). "It is reasonable to hypothesize that these relationships are less relevant in the fasting environment of elevated AgRP OGT activity, except perhaps in the case of obesity and its effects on the fasting milieu (e.g. systemically elevated glucose/insulin/lipids and ghrelin receptor desensitization)." (PMID 36111295, 2022). "To address the hypothesis that deletion of PAR2 might ameliorate age-related obesity and impaired glucose homeostasis, we assessed body composition and insulin action in 18-month-old male PAR2 knockout (PAR2KO-AG), age-matched (AG) and young C57BL6 (YG, 6-month-old) mice." (PMID 36235747, 2022). "The underlying cellular and molecular mechanisms for maternal programming of adult obesity remain unclear; in rodents, hormonal signals during early postnatal development, including leptin, insulin and ghrelin, mediate these effects—at least in part—via the CNS." (PMID 34475504, 2022). "Therefore, 2-O-M can be used as a supplement to insulin, allowing the injection of lower doses of insulin, which may reduce the potential adverse effects of injected insulin (e.g., hypoglycemia and obesity) to protect β cell function." (PMID 35502441, 2022).